MT1A (metallothionein 1A)
Diseases named in the same sentence as MT1A in open-access papers:
MT1A is named in the same sentence as 62 diseases in open-access papers, as found by Europe PMC text mining. Sharing a sentence is not in itself a finding about the gene and the disease. The quoted sentences say what the papers report.
diabetes (5 papers, 2011 to 2024). "Given its involvement in these processes, MT1A is implicated in various pathological conditions, such as diabetes, tumors and neurological disorders." (PMID 39858562, 2024). "MT1A gene in rs8052394 SNP is also most likely the predisposition gene locus for diabetes or the changes of serum superoxide dismutase activity." (PMID 25177426, 2014). "In vivo, intraperitoneal injection of Tat-MT1A in mice showed possible delivery into islets, and mice receiving 8 injections of Tat-MT1A over 11 days were partially protected against diabetes induced by multiple low doses of STZ." (PMID 33652748, 2021). "The combination Tat-MT1A + Tat-SOD1 also showed a protective effect against islet injury and delayed diabetes development in vivo." (PMID 33652748, 2021).
lung carcinoma (5 papers, 2013 to 2024). "The authors found MT-1A C/A, MT-1B G/A and MT-1F C/T variants to significantly increase the risk of lung cancer." (PMID 36981043, 2023). "It has been reported that MT1A was highly expressed and associated with shorter survival time in astrocytoma and lung cancer patients." (PMID 36387901, 2022). "In lung cancer, low expression of MT1A is associated with the tumorigenesis." (PMID 38833013, 2024). "Expression of MT-1A mRNA was decreased four-fold in lung cancers (11.59 ± 1.16 in lung cancer versus 47.03 ± 10.26 in peri-cancer tissues." (PMID 23947958, 2013). "Downregulation of MT-1A and MT-2A was found in the surgical stage of lung cancers, whereas the NRF2-targeted gene NQO1 tended to increase." (PMID 23947958, 2013). "This study investigated the expression of Nrf2 and of Nrf2-targeted genes (NQO1 and GCLC) and the genes for the metallothionein (MT) isoforms (MT-1A and MT-2A) in human lung cancer and cancer-surrounding tissues." (PMID 23947958, 2013). "A study comparing gene expression in lung tissues by microarray analysis from five patients with both lung cancer and IPF revealed five genes e.g. SMAD4, P21, MT1A, MMP7 and TIMP1; these were down-regulated in cancer tissue in comparison to IPF, in at least two of the patients." (PMID 33905434, 2021).
astrocytoma (3 papers, 2004 to 2022). "MT1A gene promoter methylation was decreased in glioblastoma (57.6%) while the gene was highly methylated in grade II-III astrocytoma (from 66.7% to 83.3%) and associated with better patient survival (p < 0.05)." (PMID 30932010, 2019). "MT1A gene methylation showed a trend of being associated with higher mRNA expression level in astrocytomas." (PMID 30932010, 2019). "In our study, methylation analysis of MT1A gene revealed gene promoter methylation in 57.6% of glioblastoma while methylation in grade III astrocytoma reached 83.3%." (PMID 30932010, 2019). "MT1A, MT1E, MT1X, MT2, MT3 gene expression was elevated in grade IV astrocytomas (glioblastomas) as compared to astrocytomas grade I-III." (PMID 30932010, 2019). "Analysis showed the trend for increasing MT1A, MT1E, MT1X, MT2 and MT3 gene expression in higher malignancy tumours, e.g. glioblastomas as compared to I-III grade astrocytomas." (PMID 30932010, 2019).
breast carcinoma (3 papers, 2014 to 2025). "MT-1A is 1 of the 4 isoforms in MT family, and aberrant MT expression has been observed in several human tumors, including EC, gallbladder cancer, B cell lymphoma, breast cancer, liver cancer, skin cancer, papillary thyroid cancer, and prostate cancer." (PMID 39998886, 2025).
glioma (2 papers, 2019 to 2022). A benign or malignant brain and spinal cord tumor that arises from glial cells (astrocytes, oligodendrocytes, ependymal cells). "Aberrant MT1A gene methylation and expression were associated with glioma progression." (PMID 34894177, 2022). "We distributed our study into three steps – determination of MT genes expression in I-IV grade glioma, thorough analysis of MT1A gene determining expression regulation through promoter methylation and clinical importance of MT gene activity." (PMID 30932010, 2019). "The analysis of MT1A gene promoter methylation using MS-PCR was determined in 50 out of 55 of the glioma patient samples used for gene expression analysis." (PMID 30932010, 2019). "Our analysis showed that the MT1A gene was methylated in 62% (31/50) of gliomas." (PMID 30932010, 2019). "The analysis of MT1A, MT1E, MT1X, MT2, MT3 gene mRNA expression was determined in n = 51, n = 53, n = 49, n = 55, n = 51 glioma patients respectively." (PMID 30932010, 2019). "Here we checked MT1A, MT1E, MT1X, MT2, MT3 gene expression level and epigenetic regulation for one of the highly expressed metallothioneins, MT1A, in different grade gliomas and looked for clinical significance of MT gene activity in glioma tissue in terms of patient survival." (PMID 30932010, 2019).
Insulin resistance (2 papers, 2015 to 2017). Increased resistance towards insulin, that is, diminished effectiveness of insulin in reducing blood glucose levels. "Malondialdehyde (MDA), total antioxidant activity (TAC), metallothionein-1A (MT-1A) gene expression, insulin resistance by the homeostatic model assessment (HOMA-IR), and urinary cadmium were investigated." (PMID 29379585, 2017).
oral cancer (2 papers, 2021 to 2023). "MT-1A polymorphism was also previously found to be associated with an increased risk of oral cancer." (PMID 36981043, 2023).
papillary thyroid cancer (2 papers, 2024 to 2025). "Similarly, significant decreases in MT1A expression have been observed in oral squamous cell and papillary thyroid carcinomas." (PMID 38833013, 2024).
type 2 diabetes (2 papers, 2021 to 2023). "Previous studies in a Chinese population corroborate our finding by revealing that the MT-1A rs11076161 was positively associated with type 2 diabetes with neuropathy and with higher cadmium blood concentration related to renal dysfunction." (PMID 33340085, 2021).
Anxiety (1 paper, 2025). Intense feelings of nervousness, tension, or panic often arise in response to interpersonal stresses. "However, in C3H/HeN mice with genetic deletion of both MT1A and/or MT1b receptors, behavioral deficits associated with impaired anxiety levels and depressive-like responses were observed." (PMID 39940805, 2025).
bladder cancer (1 paper, 2024). "Moreover, the results of differential relative expression of hub genes, SCD, DDR2, and MT1A, in bladder cancer cells compared to normal urothelial cells from RT-qPCR experiments were consistent with those of DEA on transcriptomic data from the TCGA cohort." (PMID 39107713, 2024).
cervical cancer (1 paper, 2023). A primary or metastatic malignant neoplasm involving the cervix. "The results revealed that PCK1, MT1A, AL096855.1, AC096711.2, FAR2P2, and AC099568.2 not only play a key role in the PPAR signaling pathway but also show good predictive value in cervical cancer patients." (PMID 37292383, 2023).
chronic kidney disease (1 paper, 2022). Impairment of the renal function secondary to chronic kidney damage persisting for three or more months. "Enhanced MT1A and MT2A mRNA levels in subjects with chronic kidney disease (p < 0.01) compared to NEC rather than EC, and higher metals and metalloid levels (p < 0.05) in EC compared to NEC suggest that elevated plasma burden of metals could be the reason for MT upregulation in an endemic area." (PMID 35735634, 2022).
cognitive decline (1 paper, 2025). "While MT1A expression has been linked to T-Hg exposure and cognitive decline in adults and oxidative stress due to T-Hg has been studied in adult consumers of fish, research on children remains limited." (PMID 41012407, 2025).
dilatation (1 paper, 2022). "Another study has reported an increased expression of MT1A and MT2A in the myometrium of women with arrest of cervix dilatation during labour." (PMID 36103557, 2022).
dyslipidemia (1 paper, 2022). "Interestingly, the multivariate logistic regression analysis confirmed that dyslipidemia did not contribute to the observed differences, and therefore the differences observed for MT1A, S100A6, LF, Fe and Cu are as result of AMD disease." (PMID 35426907, 2022).
endometrial cancer (1 paper, 2023). Primary or metastatic malignant neoplasm involving the endometrium (mucous membrane that lines the endometrial cavity). "Having conducted a literature review, we found no previous studies on the relationship between the polymorphisms of MT1A (rs11076161), MT2A (rs28366003) and MT1L (rs10636) and the possibility of developing endometrial cancer." (PMID 36981043, 2023). "In our study, we decided to determine the presence of MT1A (rs11076161), MT2A (rs28366003) and MT1L (rs10636) polymorphisms among the studied patients as research on the influence of the selected polymorphisms on the risk of developing endometrial cancer has not yet been conducted." (PMID 36981043, 2023).
fibrosis (1 paper, 2024). the formation of excess fibrous connective tissue in an organ or tissue in a reparative or reactive process. "However, in the fibrosis group, MT1A expression decreased following zinc supplementation despite the increased [Zn2+]i and reduced HDAC4 binding percentage." (PMID 38221603, 2024).
gastric cancer (1 paper, 2019). A primary or metastatic malignant neoplasm involving the stomach. "Notably, DNA methylation of some MT isoforms in gastric cancer, like MT1A, MT1B, MT1H, MT1M, MT3, and MT4, was higher than their paired normal tissue except remaining isoforms." (PMID 31380415, 2019).
glioblastoma (1 paper, 2019). The most malignant astrocytic tumor (WHO grade IV). "However, only MT1A and MT2 expression reached a statistically significant level (Mann-Whitney test, p < 0.05), while MT1E and MT3 genes showed the tendency of higher expression in glioblastomas (Mann-Whitney test, p = 0.120, p = 0.058 respectively)." (PMID 30932010, 2019).
hearing loss (1 paper, 2021). "In the present study, expression levels of MT1A and MT2A were increased in rats with KM-induced hearing loss and were normalized in KM + FM-treated rats." (PMID 34070066, 2021). "Furthermore, the expression levels of MT1A and MT2A and transmembrane megalin receptors were elevated in rats presenting KM-induced hearing loss." (PMID 34070066, 2021).
Hepatitis (1 paper, 2021). Inflammation of the liver. "In dogs with hepatitis, MT1A and MT2A expression levels decrease together with a copper concentration in hepatic cells." (PMID 33995471, 2021).
iron deficiency (1 paper, 2022). "We observed that MT1A mRNA levels were significantly induced when Cu and Cu with Fe were given to the basolateral side of the cells suggesting that the level of Cu in the blood might be a compelling factor for the regulation of iron deficiency-related genes in the intestine." (PMID 36494833, 2022).
lung adenocarcinoma (1 paper, 2025). A carcinoma that arises from the lung and is characterized by the presence of malignant glandular epithelial cells. "To determine the clinical relevance of the Hippo-MTF1 pathway, we analyzed data from The Cancer Genome Atlas (TCGA) regarding the expression of MTF1 and its downstream genes MT1A and MT2A in lung adenocarcinoma (LUAD) cancer patients." (PMID 39920630, 2025).
lymph node metastasis (1 paper, 2024). "Lastly, the presence of lymph node metastasis correlated with elevated risk scores and DDR2 expression but not with SCD and MT1A." (PMID 39107713, 2024).
neuroblastoma (1 paper, 2025). Neuroblastoma (NB) is the most common solid, extracranial childhood tumor. "Nevertheless, previous study reported that MT1A tranduced into the mitochondria of MPP+-treated SH-SY5Y neuroblastoma cells was able to alleviate mitochondrial damage, as shown by restored ATP levels, mitochondrial NADH dehydrogenase activity and mitochondrial superoxide levels." (PMID 39959428, 2025).
thymoma (1 paper, 2024). A neoplasm arising from the epithelial cells of the thymus. "The methylation levels of the MT1A gene were significantly elevated in TC compared to thymoma (26.4% versus 9.5%), demonstrating exceptional sensitivity and specificity in distinguishing between TCs and thymomas." (PMID 38338833, 2024). "Furthermore, no variations in the DNA methylation of MT1A and NPTX2 were identified among the several histological types of thymoma based on the WHO histologic classification." (PMID 38338833, 2024).
thyroid cancer (1 paper, 2022). "Here, we performed LASSO analysis and identified 6 critical fibroblasts related factors (PCOLCE2, APOD, APOE, TIMP1, HTRA3 and MT1A) and calculated the fibrosis scores based on their expression in patients with thyroid cancer." (PMID 36387901, 2022).
thyroid tumor (1 paper, 2022). A benign or malignant neoplasm affecting the thyroid gland. "The protein levels of HTRA3 and MT1A were significantly attenuated, but APOE protein level was increased in thyroid tumor." (PMID 36387901, 2022). "Immunohistochemical indicated that APOE stained highly in thyroid tumor, while HTRA3 and MT1A showed the reverse staining results." (PMID 36387901, 2022).
cancer (16 papers, 2007 to 2025). A tumor composed of atypical neoplastic, often pleomorphic cells that invade other tissues. "In addition, metallothionein (MT) family proteins, such as MT-2A, are highly expressed in cancer-associated fibroblasts, and the methylation of MT-1 genes (MT-1A, MT-1M, and others) is significantly higher in ESCC samples than that in normal esophageal mucosa tissue." (PMID 37840147, 2023). "Subsequently, they were verified using qMSP technology in cancer cell lines and clinical plasma samples, leading to the selection of 3 genes — MT-1A, Epo, and Septin9 — for the development of a methylation-based detection method for EC." (PMID 39998886, 2025). "TsIIA induces cancer cell apoptosis by activating calcium dependent apoptosis signal pathway and up regulating metallothionein 1A expression." (PMID 36798821, 2023). "Strikingly, members of the metallothionein family, including MT1M, MT1H, MT1G, MT1F, MT1E, MT1X, and MT1A, were significantly downregulated in cancer cells." (PMID 35967424, 2022). "MT1A gene was reported to be methylation-free in normal tissue but hypermethylated to varying extent in some cancers." (PMID 18030324, 2007). "These include research on MT-1A, Epo, and Septin9 gene methylation for auxiliary diagnosis at the Cancer Hospital of the Chinese Academy of Medical Sciences (ChiCTR2400083525), which involved a model-verification cohort of 297 participants and a clinical validation cohort of 1429 participates." (PMID 40718833, 2025). "Additionally, pan-cancer correlation analysis demonstrated that MT1A was most strongly correlated with CSRP1 in PRAD." (PMID 38833013, 2024). "Notably, the Ct values in qMSP assays showed that the differentially methylated regions on Septin9, MT-1A, and Epo genes were significantly lower in EC samples compared with controls (Wilcoxon’s test, P < 0.05), indicating these potential markers had a higher methylation status in cancer samples." (PMID 39998886, 2025). "However, previous studies have described that MT1A, compared to SOD1, has low specificity; its expression is influenced by various pollutants, including cadmium, arsenic, copper, and PM10, as well as conditions like neoplasms and cancer." (PMID 41012407, 2025).
tumor (15 papers, 2013 to 2025). "Methylation of MT-1A and MT-2A in malignant mesothelioma was shown to be associated with tumor grade histology and lymph-node involvement." (PMID 23947958, 2013). "Inflammatory pathways, such as interferon γ response, interferon α response, inflammatory response and complement pathways, were commonly upregulated in tumor samples with high MT1A expression." (PMID 38833013, 2024). "From the exploration of single-cell and bulk sequencing data for MT1A, the potential tumor-suppressor and pro-inflammatory roles were discovered." (PMID 38833013, 2024). "IHC analysis validated that the protein-level of MT1A was substantially lower in PCa tissues than in tumor-adjacent tissues." (PMID 38833013, 2024). "Metallothioneins (MTs) are small cysteine-rich proteins that play significant roles in tumor formation, progression, and drug resistance, with MT1A being one of the functional isoforms." (PMID 39351147, 2024). "We validated the transcriptional expression of identified 6 key fibrosis factors (PCOLCE2, APOD, APOE, TIMP1, HTRA3 and MT1A) in tumor and normal tissues obtained from 20 PTC patients." (PMID 36387901, 2022). "Although, Kaplan-Meier analysis for survival curves in patient groups having tumours with methylated and unmethylated MT1A gene was performed." (PMID 30932010, 2019). "Multiplex qMSP analysis of Septin9, Epo, and MT-1A showed detection sensitivities of 85.49% (95% CI, 82.55%~88.01%) for overall (n = 641) patients, and the detection performance showed positive correlation with the tumor progression." (PMID 39998886, 2025). "Finally, we identified a prominent tumor-suppressor gene, MT1A, that can serve as a valuable biomarker and explored its regulatory network." (PMID 38833013, 2024). "In order to further investigate the tumor-suppressing roles of MT1A, bayesian network models inferred that MT1A might positively regulate CSRP1." (PMID 38833013, 2024). "Decreased MT1A expression was observed in multiple tumor types." (PMID 38833013, 2024). "MT1A may also alter the TME, making it highly susceptible to a pro-inflammatory state, which is another mechanism of tumor remission." (PMID 38833013, 2024). "Large discrepancies in MT expression exist between different tumor types, and no distinct and reliable association exists between MT-1A and MT-2A expression in tumor tissues." (PMID 23947958, 2013). "However, the expression and function of MT1A in tumor progression remains controversial." (PMID 36387901, 2022). "Similarly, higher methylation in the MT1A gene was correlated with larger tumor size." (PMID 25287138, 2014). "Four genes from the metallothionein cluster on human chromosome 16q13 (MT1A, MT1E, MT1M, MT2A) were overexpressed in 231_HM.LNm5 tumours only, thus placing them in the metastatic virulence category." (PMID 29720474, 2018).
infection (2 papers, 2012 to 2022). The state of being infected such as from the introduction of a foreign agent such as serum, vaccine, antigenic substance or organism. "Furthermore, 72 h after infection, the expression levels of the metallothioneins metallothionein 2A (MT2A) (3.03) and metallothionein 1A (MT1A) (2.58) increased the most, while the lowest FC index was found for the gene encoding the calcium-binding protein S100G (−2.64)." (PMID 35746747, 2022).
MT1A also shares sentences with these, for which no sentence is quoted: Obesity (2 papers); periodontal disease (2); Alzheimer disease (1); arrhythmogenic right ventricular cardiomyopathy (1); Arthritis (1); B cell lymphoma (1); cardiac hypertrophy (1); depression (1); Down syndrome (1); E. coli infection (1); gallbladder cancer (1); leukemia (1); liver cancer (1); liver fibrosis (1); macular degeneration (1); metabolic dysfunction-associated steatohepatitis (1); metabolic dysfunction-associated steatotic liver disease (1); neurodegenerative disease (1); neurological disorders (1); neuropathy (1); nicotine addiction (1); non-small cell lung carcinoma (1); oral squamous cell carcinoma (1); osteosarcoma (1); Parkinson disease (1); poisoning (1); prostate carcinoma (1); renal dysfunction (1); skin cancer (1); Stroke (1).